CEMIP (cell migration inducing hyaluronidase 1)
Diseases named in the same sentence as CEMIP in open-access papers (continued):
Sharing a sentence is not in itself a finding about the gene and the disease.
pancreatic cancer (16 papers, 2015 to 2025). "It was first identified as a gene associated with hearing loss, but further research found that CEMIP is closely related to the progression and malignancy of various tumors, including pancreatic cancer and colorectal cancer." (PMID 37668818, 2023). "Accordingly, CEMIP has been suggested as a diagnostic serum marker for cholangiocarcinoma and pancreatic cancer." (PMID 36291875, 2022). "Here, we aimed to identify the diagnostic role of CEMIP (also called KIAA1199) combined with CA 19-9 in patients with pancreatic cancer." (PMID 29467409, 2018). "Recently, several studies have investigated the role of CEMIP in pancreatic cancer; CEMIP has been reported to be associated with early detection, cancer cell migration, invasion, and poor prognosis in previous studies." (PMID 29467409, 2018). "We investigated CEMIP and CA 19-9 levels in 324 patients with pancreatic cancer and 49 normal controls using serum enzyme-linked immunosorbent assay." (PMID 29467409, 2018). "Diagnostic role of CEMIP has been reported in pancreatic cancer." (PMID 35543351, 2022). "CEMIP synergizes with CA 19-9 in its diagnostic function for pancreatic cancer." (PMID 29467409, 2018). "Combination with CEMIP showed markedly improved AUROC over that of CA 19 − 9 alone in the diagnosis of pancreatic cancer against normal." (PMID 40610532, 2025). "Overexpression of CEMIP in pancreatic cancer cells also increased the levels of HA < 100 kDa in the extracellular milieu." (PMID 39851529, 2025). "First, this study is the first to investigate the role of CEMIP in pancreatic cancer in our locality." (PMID 40610532, 2025). "In breast and pancreatic cancers, CEMIP has been found to promote the proliferation, invasion, and metastasis of cancer cells." (PMID 37668818, 2023). "Cyclooxygenase-2 (COX-2) inhibitor NS398 suppresses CEMIP expression in colorectal adenomas, decreases CEMIP expression, and hinders migration in pancreatic cancer cells." (PMID 36291875, 2022). "Deregulated expression of CEMIP has been found in pancreatic tumors, prostate tumors, renal tumors, and breast tumors 32-35." (PMID 35370456, 2022). "The proportion of patients who showed high CEMIP levels (≥0.218 ng/ml) among pancreatic cancer patients with CA 19-9 in the normal range (<37 U/ml) was 86.1%." (PMID 29467409, 2018). "Combining the use of CA 19-9 and CEMIP significantly increased the sensitivity and specificity in discriminating not only patients with all stage pancreatic cancer, but also patients with stage I/II pancreatic cancer from healthy individuals." (PMID 30186820, 2018). "Combined use of CA 19-9 and CEMIP significantly increased the sensitivity and specificity in discriminating not only patients with all stage pancreatic cancer but also patients with stage I/II pancreatic cancer from healthy individuals." (PMID 29467409, 2018). "In conclusion, serum ELISA analysis showed that CEMIP proteins were highly expressed in patients with pancreatic cancer compared to healthy individuals." (PMID 29467409, 2018). "Combination of CA 19-9 with CEMIP showed markedly improved AUROC over CA 19-9 alone in pancreatic cancer diagnosis (0.94 vs. 0.89; P < 0.0001)." (PMID 29467409, 2018). "Using Kaplan-Meier curves, we examined the correlation between CEMIP expression and survival in patients with pancreatic cancer." (PMID 29467409, 2018). "In early-stage pancreatic cancer, combined use of CEMIP and CA 19-9 showed higher AUROC than CA 19-9 alone (0.95 vs. 0.85, P = 0.0004)." (PMID 29467409, 2018). "Combination of CA 19-9 with CEMIP showed markedly improved AUROC over that of CA 19-9 alone in the diagnosis of pancreatic cancer against healthy individuals (AUROC, 0.94 vs. 0.88; P < 0.0001)." (PMID 29467409, 2018). "Combination of CA 19-9 with CEMIP showed markedly improved AUROC over that of CA 19-9 alone in the diagnosis of pancreatic cancer against normal individuals (AUROC, 0.89 vs. 0.85; P = 0.0119)." (PMID 29467409, 2018).
pancreatic cancer (continued). "This suggests that CEMIP levels may serve as a valuable biomarker for distinguishing patients with pancreatic cancer from healthy individuals." (PMID 40610532, 2025). "Based on confirmed role of CEMIP in many malignant lesions, our rationale in the current study was to determine applicability of CEMIP in early prediction of pancreatic cancer and if it could be used as a promising biomarker in this area." (PMID 40610532, 2025). "Serum CEMIP may serve as non-invasive biomarkers for diagnosis of pancreatic cancer patients in comparison to other conventional biomarkers." (PMID 40610532, 2025). "Recently, a novel point has explored the relationship between CEMIP and pancreatic cancer." (PMID 36451490, 2022). "First, this study is the largest to investigate the role of CEMIP in pancreatic cancer." (PMID 29467409, 2018). "This study describes a novel biomarker, CEMIP, which may be used in combination with CA 19-9 in whole blood in the diagnosis of pancreatic cancer." (PMID 29467409, 2018). "Moreover, CEMIP also exhibited significantly higher expression levels in patients with pancreatic cancer than in normal individuals (0.67 vs. 0.16 ng/ml, P < 0.001)." (PMID 29467409, 2018). "Therefore, we aimed to investigate the differences in CEMIP expression in whole blood between patients with pancreatic cancer and healthy participants, and to identify the role of CEMIP compared with that of CA 19-9 in the diagnosis of pancreatic cancer." (PMID 29467409, 2018). "Especially, CEMIP may be a complementary marker in pancreatic cancer patients with normal CA 19-9 levels." (PMID 29467409, 2018). "Proteins such as CEMIP can be used for pancreatic cancer detection." (PMID 30186820, 2018). "Several studies have explored the role of cell migration-inducing protein (CEMIP) in pancreatic cancer (PC), suggesting that CEMIP may be involved in early tumor detection, cancer cell migration, invasion, and is frequently associated with unfavorable prognosis across various malignancies." (PMID 40610532, 2025). "Interestingly, ANXA1 has been reported to positively regulate cellular motility in pancreatic cancer, which could conceivably link the CEMIP hyaluronidase activity with increased motility, although this remains to be investigated." (PMID 36291875, 2022). "Therefore, combined detection with serum CA 19-9 and CEMIP levels may have the potential to become a new laboratory method for the clinical diagnosis of pancreatic cancer." (PMID 29467409, 2018). "It was found that CEMIP had positive significant correlations with CA19-9 (r = 0.37, p < = 0.01) and CEA (p = 0.65, p = 0.001) in patients with pancreatic cancer." (PMID 40610532, 2025). "PC: pancreatic cancer; CEA: carcinoembryonic antigen; CA19-9: cancer antigen 19 − 9; CEMIP: cell migration inducing protein." (PMID 40610532, 2025). "PC: pancreatic cancer; CEA: carcinoembryonic antigen; CA19-9: cancer antigen 19 − 9; CEMIP: cell migration inducing protein; PPV: positive predictive value; NPV: negative predictive value; AUC: area under curve." (PMID 40610532, 2025). "Combined ROC curve analysis using CA 19-9 and CEMIP revealed an AUROC of 0.89 (95% CI: 0.862–0.920) with a sensitivity of 80.3% and a specificity of 97.9% in discriminating pancreatic cancer patients from normal individuals." (PMID 29467409, 2018).
hearing loss (13 papers, 2010 to 2024). "The characterization of additional hearing-loss subjects with CEMIP variants is needed to further assess CEMIP’s role in hearing loss." (PMID 39056785, 2024). "CEMIP, also known as KIAA1199, was initially identified as a protein in the inner ear, and mutations in its genetic makeup were associated with nonsyndromic hearing loss." (PMID 38835051, 2024). "In this review, we summarize the cellular signaling pathways that CEMIP involves, describe the role of CEMIP in different cancers and hereditary hearing loss, and discuss the prospects of CEMIP research." (PMID 36451490, 2022). "CEMIP is a prominent element in hearing loss, keratoconus with cataracts, rheumatic heart, osteoarthritis, and cancers as a multidomain protein involved in various interacting pathways." (PMID 36451490, 2022). "It has been reported that CEMIP mutation in the GG domain leads to non-syndromic hearing loss, while its over-expression prevailingly contributes to its oncogenic roles." (PMID 34966410, 2021). "CEMIP is a kind of secreted protein, identified as an inner ear-specific protein at first, and mutations in it are related to non-syndromic hearing loss." (PMID 34966410, 2021). "CEMIP (CEll Migration-Inducing Protein) also known as KIAA1199 or HYBID (hyaluronan-binding protein) was identified as a cause of non-syndromic hearing loss in four Japanese families during a screen of 52 genes that are specifically or preferentially expressed in the inner ear." (PMID 39056785, 2024). "Based on the screening results of the CEMIP gene for mutations in patients with nonsyndromic hearing loss in Japan, 3 possible point mutations related to this disease are selected: an Arg187-to-Cys (R187C) mutation, an Arg187-to-His (R187H) mutation, and a His783-to-Tyr (H783Y) mutation." (PMID 36451490, 2022). "Three different missense substitutions in CEMIP, NM_001293298.2: c.559C>T (p.R187C), c.560G>A (p.R187H) and c.2347C>T (p.H783Y) were identified; two (R187C and R187H) were found in familial cases of hearing loss and one (H783Y) was found in a sporadic case of hearing loss." (PMID 39056785, 2024). "KIAA1199, also known as cell migration inducing protein (CEMIP) or hyaluronan binding protein (HYBID), was reported to cause non-syndromic hearing loss and depolymerize hyaluronic acid (HA)." (PMID 36419650, 2022).
osteoarthritis (13 papers, 2014 to 2025). A noninflammatory degenerative joint disease occurring chiefly in older persons, characterized by degeneration of the articular cartilage, hypertrophy of bone at the margins and changes in the synovial membrane. "This upregulation of CEMIP reflects pathological features observed in fibrotic diseases, rheumatoid arthritis and osteoarthritis, which share common inflammatory pathways." (PMID 40400122, 2025). "Such a scenario is validated by previous research identifying heightened CEMIP expression in the chondrocytes and synovial fibroblasts of osteoarthritis patients, implicating it as a driver of HA degradation and associated pathophysiological changes." (PMID 40400122, 2025). "The pathological implications of elevated CEMIP levels, similar to those found in osteoarthritis and rheumatoid arthritis, are notable for their potential to accumulate LMW‐HA, thus promoting a microenvironment beneficial to angiogenesis and inflammation." (PMID 40400122, 2025). "In conclusion, we clarified the regulatory mechanism of CEMIP in chondrocytes by inflammatory cytokines and suggested the potential involvement in osteoarthritis development." (PMID 32365591, 2020). "In this study, CEMIP expression is investigated in healthy and osteoarthritis (OA) cartilage from human and mouse." (PMID 30718510, 2019). "In periarticular tissue, inflammatory cytokines induced the expression of CEMIP, which suggests that it may play a significant role in the initiation or development of osteoarthritis." (PMID 38835051, 2024). "Finally, in a mechanically-induced knee osteoarthritis model, cartilage destruction and osteophyte formation were reduced in CEMIP ΔE1 mice, suggesting a role for HA degradation by CEMIP in osteoarthritis progression." (PMID 39056785, 2024). "A previous study indicated that CEMIP induced chondrocyte fibrosis in osteoarthritis." (PMID 37313693, 2023). "Notably, the CEMIP-dependent degradation of HA by fibroblasts in inflammatory diseases such as Crohn’s disease and osteoarthritis creates a pro-inflammatory environment due to the accumulation of degraded HA oligosaccharides." (PMID 36291875, 2022). "Furthermore, CEMIP is increased in synovial fibroblasts from patients with osteoarthritis (OA) and rheumatoid arthritis (RA) and is detected in the synovium of RA patients and referred to as an angiogenic marker." (PMID 30718510, 2019).
rheumatoid arthritis (10 papers, 2014 to 2025). A chronic, systemic autoimmune disorder characterized by inflammation in the synovial membranes and articular surfaces. "IL-6 activating NF-κB via phosphatidylinositol 3-kinase (PI3K)/protein kinase B (PKB/AKT) signaling is thought to be the main pathway for inducing CEMIP expression in rheumatoid arthritis (RA) fibroblast-like synoviocytes (FLSs)." (PMID 37662915, 2023). "Previously, CEMIP was also found to participate in the degradation of hyaluronic acid in rheumatoid arthritis." (PMID 34338150, 2021). "In rheumatoid arthritis, CEMIP is referred to as an angiogenic marker and participates in hyaluronic acid degradation." (PMID 30718510, 2019). "Moreover, it was also evidenced that CEMIP was upregulated in synovial fibroblasts in Rheumatoid Arthritis (RA) or Osteoarthritis (OA) patients." (PMID 39481283, 2024).
adenoma (7 papers, 2010 to 2025). A neoplasm arising from the epithelium. "Among them, two up-regulated (ADAM12, CEMIP) and one down-regulated (HHLA2) hub-genes have not been majorly highlighted for their contribution to adenoma-carcinoma transition, to the best of our knowledge." (PMID 38698020, 2024).
lung cancer (7 papers, 2017 to 2025). A malignant neoplasm involving the lung. "In nonsmall cell lung cancer cells, reduced CEMIP suppresses proliferation and migration of nonsmall cell lung cancer cells and down-regulated the expression of several transcription factors related to the EMT process and EGFR signaling." (PMID 36451490, 2022). "Consistently, CEMIP expression in human primary breast and lung cancers has been found to correlate with metastasis formation and poor prognosis, and brain metastases have been found to exhibit significantly higher CEMIP levels." (PMID 36291875, 2022). "Interestingly, the overexpression of cell migration‐inducing and hyaluronan‐binding protein (CEMIP) has been reported to promote the metastasis of other cancers, such as lung cancer, to the brain, which was further validated in this dataset." (PMID 39716938, 2025).
ovarian carcinoma (7 papers, 2019 to 2023). A malignant neoplasm originating from the surface ovarian epithelium. "CEMIP, downregulated by both kaempferol and progesterone treatments, is upregulated in the tumor tissues of patients with epithelial ovarian cancer." (PMID 36986136, 2023). "Knockdown of CEMIP is also shown to decrease oncogenic properties, including proliferation, invasion, and migration, in a human ovarian cancer cell line." (PMID 36986136, 2023). "Ovarian cancer cells’ migration and invasion capacity are significantly decreased, and the proportion of apoptotic cells increases after silencing CEMIP." (PMID 36451490, 2022). "Over-expression of CEMIP promoted cell invasion and metastasis of ovarian cancer, and CEMIP protein secreted by tumor exosomes promoted brain cancer cell colonization and metastasis." (PMID 35543351, 2022). "Some researchers have studied the PI3K-AKT signaling pathway, which affects cell proliferation and migration in cancers and is activated by CEMIP in promoting ovarian cancer tumorigenesis and progression." (PMID 31396530, 2019). "CEMIP was found to play an essential role in ovarian cancer progression." (PMID 36451490, 2022). "CEMIP expression is significantly upregulated in ovarian cancer tissues." (PMID 36451490, 2022).
Arthritis (6 papers, 2020 to 2023). Inflammation of a joint. "At the functional level, CEMIP deficiency has been shown to suppress experimentally induced arthritis in mice, which can be reversed through adenoviral-delivered CEMIP in a manner that depends on the G8 domain." (PMID 36291875, 2022). "Originally discovered as a hypothetical protein with unknown function, CEMIP (cell migration-inducing and hyaluronan-binding protein) has been implicated in the pathogenesis of numerous diseases, including deafness, arthritis, atherosclerosis, idiopathic pulmonary fibrosis, and cancer." (PMID 36291875, 2022). "In recent years, some studies have reported that CEMIP can promote the proliferation, invasion, and adhesion of various tumor cells and can play an important role in bacterial infection and arthritis." (PMID 37662915, 2023). "Indeed, CEMIP induced degradation of high HA in skin and arthritis synovial fibroblasts through its N-terminal sequence, leading to small HA fragments enhancing inflammation." (PMID 35474501, 2022). "The HA network in the synovial tissue may also be critical in relation to the role of CEMIP in human arthritis." (PMID 32365591, 2020). "In addition to its overexpression in arthritis tissues, it is increasingly apparent that CEMIP could play a critical role in pathology development." (PMID 35474501, 2022). "Antibodies that neutralize the hyaluronidase activity of CEMIP have shown utility in the context of experimentally induced arthritis, and it would be interesting to see whether a similar approach might have an impact in the context of tumorigenesis and metastasis." (PMID 36291875, 2022).
colon adenocarcinoma (6 papers, 2010 to 2022). "A previous report, utilizing DNA microarray, demonstrated that 95% of 511 colon adenocarcinoma tissues displayed upregulated CEMIP." (PMID 26009875, 2015). "Moreover, nuclear CEMIP protein expression is positively correlated with the expression of nuclear beta-catenin in colon adenocarcinomas tissues." (PMID 34680448, 2021). "In MC38 colon adenocarcinoma cells, pirfenidone suppresses CEMIP expression and improves the response to PD-1 blockade in experimental animals through fostering the infiltration of CD8+ T cells, which is regulated at least in part by CEMIP." (PMID 36291875, 2022).
invasive breast carcinoma (6 papers, 2014 to 2024). A carcinoma that infiltrates the breast parenchyma. "CEMIP is upregulated in invasive breast cancer specimens and contributes to a poor prognosis for patients." (PMID 38971758, 2024).